ALB (albumin)
Diseases named in the same sentence as ALB in open-access papers (continued):
Sharing a sentence is not in itself a finding about the gene and the disease.
Ewing sarcoma (2 papers, 2023 to 2024). A small round cell tumor that lacks morphologic, immunohistochemical, and electron microscopic evidence of neuroectodermal differentiation. "Recent studies examined the CRP–albumin ratio (CAR), showing that higher CAR levels were associated with poor prognosis in Ewing’s sarcoma." (PMID 39001318, 2024).
Fabry disease (2 papers, 2015 to 2019). Fabry disease (FD) is a progressive, inherited, multisystemic lysosomal storage disease characterized by specific neurological, cutaneous, renal, cardiovascular, cochleo-vestibular and cerebrovascular manifestations. "This emphasizes the importance of follow-up and monitoring of albumin/creatinine ratio at least annually in children with Fabry disease." (PMID 25955246, 2015).
femoral neck fracture (2 papers, 2024 to 2025). Fractures of the short, constricted portion of the thigh bone between the femur head and the trochanters. "Serum albumin level (<3.5 g/dL) on admission was reported to be a useful factor in predicting 1-year mortality in patients undergoing surgery for femur neck fracture (p = 0.0049)." (PMID 39518469, 2024). "Patients in the intertrochanteric fracture group had significantly lower red blood cell counts, hemoglobin, albumin, total cholesterol, and serum calcium levels compared to the femoral neck fracture group (P < .001), but higher blood urea nitrogen levels (P = .01)." (PMID 40550046, 2025).
gastric disease (2 papers, 2021 to 2025). "It has been speculated that protein and albumin loss in MD is a consequence of gastric tight junctional complex widening, and therefore, this protein-losing gastropathy is a potentially lethal disease." (PMID 41040501, 2025). "Additionally, studies on the mechanism of hypoproteinemia in GC found that a massive leakage of serum albumin into the stomach occurs often in GC as well as other gastric disease." (PMID 34568007, 2021).
Gastrointestinal obstruction (2 papers, 2023 to 2024). "The results demonstrated that tumor size, plasma albumin level, preoperative gastrointestinal obstruction and vomiting, and TNM stage were associated with a larger GV to body weight (> 1.5 ml/Kg), suggesting a high aspiration risk." (PMID 38433227, 2024).
gastrointestinal stromal tumor (2 papers, 2020 to 2023). "Herein, we examined the role of fibrinogen-to-albumin ratio index (FARI) in the prognosis of gastrointestinal stromal tumors (GISTs) and developed a novel nomogram predicting recurrence-free survival (RFS)." (PMID 33014783, 2020).
glucose metabolism disorders (2 papers, 2022 to 2025). "This study investigates the possible utility of glycated albumin as an alternative biomarker for diagnosing glucose metabolism disorders in transfusion-dependent patients." (PMID 40924301, 2025).
graft versus host disease (2 papers, 2008 to 2026). An immune system disorder that occurs after allogeneic hematopoietic stem cell transplant and is a reaction of donor immune cells against host tissues. "There are also characteristic salivary changes in case of graft-versus-host disease including the elevated concentration of total protein, albumin, EGF, IgG, and a decreased amount of IgA and IgM in the saliva." (PMID 19424479, 2008).
granulocytopenia (2 papers, 2025). "In the first model, both SMI and serum albumin had P-values < 0.05, indicating their significant impact on the occurrence of granulocytopenia." (PMID 40260254, 2025). "Two models were constructed for granulocytopenia incidence: one included SMI (P=0.011) and serum albumin (P<0.001), while the other included SMI (P=0.673) and drug dose (P=0.076)." (PMID 40260254, 2025).
Hand-foot syndrome (2 papers, 2017 to 2023). "Abdominal pain, fever, nausea and vomiting, fatigue, decreased albumin, PLT, WBC, elevated AST, and hand-foot syndrome are common adverse events in patients receiving TACE." (PMID 37936761, 2023).
Hashimoto's disease (2 papers, 2013 to 2026). "In the analysis of female patients, variables identified by the same method included Brinkman index, the serum albumin levels, the serum AST levels, the platelet counts, and the past history of Hashimoto's disease." (PMID 23533384, 2013). "In the analysis of overall patients, these variables included Brinkman index (number of cigarettes per day × years of smoking), the serum albumin levels, the serum AST levels, the platelet counts, and the past history of Hashimoto's disease." (PMID 23533384, 2013).
Hemophagocytosis (2 papers, 2019 to 2020). Phagocytosis by macrophages of erythrocytes, leukocytes, platelets, and their precursors in bone marrow and other tissues. "Multivariate Cox analysis showed that albumin < 25 g/L (p = 0.017), HGB < 60 g/L (p = 0.027), and bone marrow hemophagocytosis (p = 0.034) correlated with worse prognosis." (PMID 31783813, 2019). "Multivariate analysis showed that albumin < 25 g/L (p = 0.017), HGB < 60 g/L (p = 0.027), and bone marrow hemophagocytosis (p = 0.034) correlated with poor prognosis." (PMID 31783813, 2019). "The multivariate analysis showed that HGB < 60 g/L (p = 0.027), albumin < 25 g/L (p = 0.017), and bone marrow hemophagocytosis (p = 0.034) were negative prognostic factors for both groups." (PMID 31783813, 2019).
Hepatosplenomegaly (2 papers, 2020 to 2022). Simultaneous enlargement of the liver and spleen. "The univariate analysis showed that age, Cr, ALB, PLT, LYR, Hb, FIB, ALT, etiologies, and gender significantly affected survival in the derivation cohort, whereas hepatosplenomegaly did not." (PMID 35251016, 2022).
high-grade glioma (2 papers, 2011 to 2017). "This retrospective study was designed to determine the prognostic value of a cumulative score (FA score) based on pretreatment plasma fibrinogen and serum albumin levels for 326 patients newly diagnosed high-grade glioma (HGG)." (PMID 28548947, 2017). "In a recent review, up-regulation of serum albumin and apolipoprotein-A1 were commented as the consequence of the blood brain barrier degradation in malignant gliomas." (PMID 21470419, 2011).
hyperandrogenism (2 papers, 2013 to 2021). Excessive secretion of androgens from the adrenal glands or gonads. "Hyperandrogenism is often a common feature between the two conditions and in both, the manifestation of this hyperandrogenism may not correlate with the circulating androgen levels because total circulating testosterone is mostly bound to albumin and sex-hormone binding globulin." (PMID 24719635, 2013). "No less important is that the mixed ketogenic diet resulted in an increase in albumin and SHBG, both free testosterone binding proteins, with a consequent reduction in bioactive free testosterone, thus contributing to a further improvement of hyperandrogenism." (PMID 34886216, 2021).
Hypoadiponectinemia (2 papers, 2018 to 2021). "The mechanism is still unknown in humans but has been investigated in mice with hypoadiponectinemia and albuminuria (a pathological condition where the protein albumin is abnormally present in the urine) in which a link between hypoadiponectinemia and kidney dysfunction has been demonstrated." (PMID 29636702, 2018).
hypoxia (2 papers, 2019 to 2025). A decrease in the amount of oxygen in the body. "Although a recent manuscript reported that inhibition of VCAM1 activation protects against BBB breakdown in a mouse model of chronic cerebral hypoxia, in our experiments VCAM-1 blockade alone did not reduce albumin extravasation." (PMID 40259346, 2025).
hypoxic-ischemic encephalopathy (2 papers, 2015 to 2020). "Out of 303 patients with SE, 58 patients with hypoxic-ischemic encephalopathy and 154 patients without measurements of acute-phase proteins (i.e., serum levels of PCT, CRP and albumin) within the first 24 hours after SE onset were excluded." (PMID 26450065, 2015).
iron disorder (2 papers, 2014 to 2025). "Compared with patients with no iron disorder, those with non-inflammatory functional ID had higher BMI and CRP values and lower serum albumin levels." (PMID 24586229, 2014).
Lassa fever (2 papers, 2020 to 2021). A viral hemorrhagic fever that is caused by the Lassa virus, which is transmitted by contact with infected rodents; it is characterized by fever, headache, malaise, myalgia, and hearing loss. "Distribution of albumin-to-globulin ratio among the Lassa fever-infected patients during admission." (PMID 33312698, 2020).
leukoaraiosis (2 papers, 2023 to 2025). "Patients with leukoaraiosis showed a 34% increase in the CSF-to-serum albumin ratio, signifying a breakdown in the blood–brain barrier." (PMID 41008383, 2025).
lichen planus (2 papers, 2012 to 2025). A chronic, recurrent, pruritic inflammatory disorder of unknown etiology that affects the skin and mucus membranes. "According to multivariate analysis, three factors, positivity for HCV RNA, low albumin level (< 4.0 g/dL), and history of smoking, were associated with the development of lichen planus." (PMID 22490000, 2012). "However, further prospective studies may confirm the association between C-reactive protein-to-albumin ratio and lichen planus." (PMID 40172389, 2025). "Elevated C-reactive protein-to-albumin ratio levels may be considered a potential marker for lichen planus." (PMID 40172389, 2025). "Since lichen planus is a chronic inflammatory disease, our study aimed to investigate the relationship between C-reactive protein-to-albumin ratio and disease activity and whether it plays a role in determining disease prognosis, and compare them with those in subjects without lichen planus." (PMID 40172389, 2025).
limb ischemia (2 papers, 2021 to 2022). A ischemia that involves the limb. "Again, recent studies have shown that low prognostic nutritional index (PNI), a marker-based on albumin and neutrophils, in patients with limb ischemia causes more critical limb ischemia and amputations." (PMID 35902808, 2022).
liver hemangioma (2 papers, 2016 to 2020). A hemangioma arising from the liver. "A previous study in humans already utilized albumin indirectly labeled with 68Ga-EB as a blood pool marker to differentiate liver hemangiomas, which showed increased activity, compared to focal hepatic lesions showing decreased activity." (PMID 34766000, 2020). "Liver hemangiomas have been described previously in germline Vhlh+/- mice and in mice with Vhlh inactivation in hepatocytes (PEPCK-Cre or Albumin-Cre driven Vhlh knockout mice)." (PMID 27733136, 2016).
macrosomia (2 papers, 2022 to 2024). "With increase in albumin concentrations, that is, from Q1 to Q4, the rates of PTB, LBW, SGA, and VSGA significantly increased (P = 0.036 for PTB; P < 0.001 for the rest), whereas the rates of macrosomia, LGA, and VLGA decreased (P < 0.001 for all)." (PMID 38505758, 2024).
manic episodes (2 papers, 2022 to 2023). "When compared to the females, the males in the BD manic episodes group presented higher neutrophil, lymphocyte, albumin and RPR values (P < 0.05), and lower platelet, MPV, PDW, PCT, RDW, PLR and PAR values (P < 0.05)." (PMID 35216557, 2022). "When compared to the BD manic episodes group, the RDW and PLR values in the MDD group were increased (P < 0.05), the MPV, PCT, neutrophil counts, lymphocyte counts, albumin and SII values in MDD group were decreased (P < 0.05)." (PMID 35216557, 2022). "In the BD manic episodes group, the PLR and RPR values were positively correlated with age (P < 0.05), and the platelet, MPV, PCT, neutrophil, lymphocyte and albumin values were negatively correlated with age (P < 0.05)." (PMID 35216557, 2022).
medulloblastoma (2 papers, 2021 to 2024). A malignant, invasive embryonal neoplasm arising from the cerebellum. "In both cohorts, Albumin (ALB) was the highest-ranking CSF protein for both medulloblastoma patients and controls." (PMID 38350915, 2024). "Catanzaro and collaborators developed redox-responsive bovine serum albumin NPs for the cisplatin release in medulloblastoma treatment." (PMID 34066953, 2021). "Albumin nanocarriers were in vitro tested on Daoy medulloblastoma and healthy cells." (PMID 34066953, 2021).
Miscarriage (2 papers, 2014 to 2026). A pregnancy that ends at a stage in which the fetus is incapable of surviving on its own, defined as the spontaneous loss of a fetus before the 22th week of pregnancy. "Conversely, the neutrophil-to-lymphocyte ratio (NLR), fibrinogen, and the fibrinogen-to-albumin ratio (FAR) were elevated in the early missed miscarriage group compared with the control group (p < 0.05)." (PMID 41958595, 2026). "Other proteins that were significantly increased in the obese miscarriage group were transthyretin (pre-albumin), and beta globin." (PMID 25096020, 2014).
mucormycosis (2 papers, 2024 to 2025). "Strikingly, we found thatpurified albumin selectively inhibits Mucorales growth among a range of human pathogens,and albumin-deficient mice display susceptibility specifically to mucormycosis." (PMID 39678331, 2024). "The striking correlation between albumin level and the antifungal activity ofserum from patients at risk for mucormycosis, prompted us to evaluate the direct inhibitoryeffect of albumin on Mucorales." (PMID 39678331, 2024). "Selective inhibitory activity of human albumin against Mucorales and association ofserum albumin level with mucormycosis outcome." (PMID 39678331, 2024). "Our initial studies revealedan intriguing association between low albumin level and the development of mucormycosis inhigh-risk patients with hematological malignancies." (PMID 39678331, 2024). "Albumin knockout mice display selective susceptibility to mucormycosis." (PMID 39678331, 2024). "Collectively, these findingsidentify a specialized role of albumin-bound FFAs in immunity against Mucorales withimportant implications in the pathogenesis of mucormycosis." (PMID 39678331, 2024). "Studies in mouse models of disseminated mucormycosis and pulmonary fungalinfection by A. fumigatus and Mucorales in albumin-KO humanized miceprovided additional definitive evidence for a non-redundant, specialized role of albumin inimmunity against Mucorales." (PMID 39678331, 2024). "To gain mechanistic insight into the physiological importance of albumin inantifungal immunity we employed pathophysiologically relevant in vivomodels of mucormycosis in immunocompetent and neutropenic mice." (PMID 39678331, 2024). "Given the lack of host biomarkers for prognostication of mucormycosis,albumin level should be further investigated as a readily available, inexpensive anduniversal biomarker to stratify patients at risk and predict infection outcome." (PMID 39678331, 2024).
mycotoxicosis (2 papers, 2022 to 2025). Poisoning caused by the ingestion of mycotoxins (toxins of fungal origin). "Conversely, during mycotoxicosis, serum total protein and albumin concentrations in chickens may be reduced due to the inhibition of amino acid transport and mRNA transcription, and the potential direct interaction of DON with ribosomal units, leading to the inhibition of protein synthesis." (PMID 35622561, 2022).
myelofibrosis (2 papers, 2022 to 2023). A partial or complete replacement of the bone marrow stroma by fibrous tissue. "In myelofibrosis, the C-reactive protein (CRP)/albumin ratio (CAR) and the Glasgow Prognostic Score (GPS) add prognostic information independently of the Dynamic International Prognostic Scoring System (DIPSS)." (PMID 36900271, 2023).
Nematode infection (2 papers, 2012 to 2025). "Nematode infection has been observed to cause a decrease in albumin and increase in globulin mainly due a rise in the antibodies." (PMID 23109947, 2012). "ALB and TP levels, often suppressed in severe nematode infections due to malabsorption and catabolism, were low at baseline across all groups." (PMID 40926855, 2025).
Nephrotic range proteinuria (2 papers, 2018 to 2023). Severely increased amount of excretion of protein in the urine, defined as 3.5 grams per day or more in adults and 40 mg per meter-squared body surface area per hour in children. "Other in vitro studies reported that podocytes from patients with nephrotic-range proteinuria or podocytes from mice exposed to albumin, resulted in p38MAPK-mediated apoptosis." (PMID 30573754, 2018).
nephrotoxicity (2 papers, 2015 to 2024). Toxicity that causes injury to the kidney or damages its function. "In bivariate analysis, patients with nephrotoxicity were significantly older (P 0.013) and had lower baseline serum albumin (P 0.008)." (PMID 25591721, 2015). "Centella asiatica extract lowered serum creatinine and oxidativestress levels in a drug-induced nephrotoxicity rat model, while simultaneously increasing serum albumin levels, as evidenced bymitigation of histological changes and normalisation of biomarkers of oxidative stress in the kidney." (PMID 39132239, 2024).
neurotoxicity (2 papers, 2015 to 2025). Toxicity that causes injury to the central or peripheral nervous system or damages its function. "Neurotoxicity is caused by the fraction of unconjugated bilirubin not bound to albumin (free bilirubin, Bf)." (PMID 26541892, 2015).
non-alcoholic fatty liver (2 papers, 2017 to 2025). A benign form of fatty non-alcoholic fatty liver disease where the disease has not yet progressed to the inflammation of liver. "Note: CI, confidence interval; HR, hazard ratio; NAFLD, non-alcoholic fatty liver; NASH, non-alcoholic steatohepatitis; n, sample size; OR, odds ratio. aUrinary albumin to creatinine ratio ≥ 30 mg/g creatinine. bEstimated glomerular filtration rate (eGFR) < 60 mL/min/1.73 m2." (PMID 28248635, 2017).
Onset (2 papers, 2022 to 2023). The age group in which disease manifestations appear. "For all patients, POAF occurred in 43% of the albumin subgroup and 47% of the mannitol subgroup (p = .53) and for patients with new‐onset AF, POAF occurred in 35% of the albumin subgroup versus 42% of the mannitol subgroup (p = .36)." (PMID 36116062, 2022).
oral candidiasis (2 papers, 2024 to 2025). Infection of the mucosal lining of the mouth with the fungus Candida albicans. "The consistently lower albumin levels observed among children with oral candidiasis in this study may therefore reflect a combination of systemic nutritional insufficiency and heightened metabolic demands associated with subclinical inflammatory processes." (PMID 40507084, 2025). "Serum ALB, IgG, IgA, and IgM levels, the total number of T cells, B cells, and NK cells, and the number of Th cells were considerably lower in individuals with oral candidiasis than in those without oral candidiasis (P < 0.05)." (PMID 39020326, 2024).
ovarian clear cell cancer (2 papers, 2020 to 2022). An invasive malignant neoplasm that arises from the ovary and is characterized by a predominance of clear and hobnail malignant epithelial cells. "This study aims to evaluate the role of the fibrinogen/albumin ratio (FAR) in predicting platinum resistance and survival outcomes of patients with ovarian clear cell carcinoma (OCCC)." (PMID 35062908, 2022). "Preoperative leukocyte differential counts, as well as platelet, serum albumin, plasma D-dimer and CA-125 levels, were measured in patients with FIGO IC-IV ovarian clear cell cancer." (PMID 32771026, 2020).
overactive bladder (2 papers, 2021 to 2024). Symptom of overactive detrusor muscle of the urinary bladder that contracts with abnormally high frequency and urgency. "A low platelet and low serum albumin level in these patients may be predictors for overactive bladder." (PMID 34198972, 2021).
pancreatic NET (2 papers, 2020 to 2025). "In a subgroup analysis, albumin, CRP and GPS remained associated with OS in SI‐NET, pancreatic NET and NET of other origin." (PMID 38477040, 2025).